TNF (tumor necrosis factor)
Diseases named in the same sentence as TNF in open-access papers (continued):
Sharing a sentence is not in itself a finding about the gene and the disease.
synovial sarcoma (7 papers, 2013 to 2025). "For example, both LL-37 and IL-17A were shown to induce the transcription of TNFα in human synovial sarcoma cells, and LL-37 with IL-1β was demonstrated to synergistically increase IL-8 production in airway epithelial cells." (PMID 40410820, 2025). "Human synovial sarcoma cells (SW982) were used to examine the effects of bromelain on TNF-α–mediated inflammation in this study." (PMID 34834636, 2021). "Synovial sarcoma showed inhibition of MMP-2 with TNF-α and slight stimulation of MMP-9 at 10 ng/ml." (PMID 24085323, 2013).
thrombotic disease (7 papers, 2014 to 2025). The formation of a blood clot in the lumen of a vessel or heart chamber; causes include coagulation disorders and vascular endothelial injury. "LiC has been widely used in the treatment of thrombotic diseases and can reduce the levels of pro-inflammatory cytokines (IL-1β, TNF-α)." (PMID 34992529, 2021). "Through the approach of network pharmacology, 34 signal pathways were predicted to be involved in thrombus (including MAPKs, VEGF, and TNF), and the role of MAPKs signal pathway in thrombotic diseases was verified." (PMID 32477130, 2020). "Systemic inflammation can induce systemic hypercoagulability, and many inflammatory chemokines such as for tumor necrosis factor-α (TNF-α), interleukin-1β (IL-1β), and IL-6, are involved in the formation of thromboses." (PMID 41235099, 2025). "Considering that TNFα was identified as an upstream regulator in the HCM LA and IL6 was found to be relevant in HCM (particularly in cats with atrial thrombus), an involvement of T cells in atrial changes in HCM seems likely." (PMID 36928240, 2023).
thymic atrophy (7 papers, 2012 to 2024). "In Harbor porpoises, neither IL-6 nor TNF-α were associated with severely diseased individuals, those with splenic depletion, or the degree of thymic atrophy." (PMID 36230446, 2022). "We observed that TPSs significantly increased the body weight and alleviated CTX-induced thymus atrophy in the immunosuppressed mice; they also increased the plasma levels of immunoglobulins A and M, interleukin (IL) 1β, IL-6, inducible nitric oxide synthase, and tumor necrosis factor α." (PMID 39335922, 2024). "During infection, cytokines such as IL-1, IL-6, and TNF-α are obviously elevated, which stimulates the hypothalamic-pituitary-adrenal (HPA) axis and then increases the production of glucocorticoid, which is the main course of thymic atrophy." (PMID 34113341, 2021). "In addition, in Plasmodium infection, TNF-α has a protective effect on the thymus, while the increase of TNF-α during T. cruzi infection exacerbates thymic atrophy." (PMID 34113341, 2021).
thymoma (7 papers, 2017 to 2025). A neoplasm arising from the epithelial cells of the thymus. "Our Study reveals that TNF could serve as a potential target for methylprednisolone treatment of Thymoma-associated MG, and Cer and SM could act as potential metabolic biomarkers to assess its treatment efficacy." (PMID 40418396, 2025). "Based on the TCGA dataset, we also showed that IFN-γ, ICAM1, and TNF expression were decreased in thymoma; however, CCL2 expression was considerably increased." (PMID 37644514, 2023). "We identified three pathways, TNF-alpha signaling, MacTh1 cluster, and Chemokine signaling that were significantly downregulated in MG+ type AB thymoma." (PMID 32373124, 2020). "Here we focussed on NF-κB-driven cFLIP expression because it is common in many cancers Indeed, the NF-κB inhibitor, EF24 elicited cFLIP downregulation in primary thymoma TECs and 1889 thymic carcinoma cells and sensitized them to TNFα induced cell death." (PMID 29163772, 2017). "This treatment reduced cFLIP mRNA and protein expression levels and facilitated TNFα-induced cell death in neoplastic pTECs of two B3 thymomas tested in passage 1 and 2 (left diagram, 2nd column)." (PMID 29163772, 2017). "Since survival of primary cell cultures established from thymomas was significantly attenuated by TNFα treatment only after cFLIP knockdown, increased cFLIP expression appears to be functionally relevant." (PMID 29163772, 2017). "Network pharmacology analysis revealed that tumor necrosis factor (TNF) could serve as a potential target for methylprednisolone treatment of thymoma with MG." (PMID 40418396, 2025). "By contrast, we report here that there is increased expression of cellular FLICE-like inhibitory protein (cFLIP), a key inhibitor of the extrinsic, TNFα-, FAS-L- and TRAIL-driven apoptosis pathway, in both thymomas and TSCCs compared to NT." (PMID 29163772, 2017). "The hsa_circ_0001173 has been reported to be significantly upregulated in thymoma and might participate in the abnormal immune regulation of thymus through cell–cell adhesion, MAPK pathway and tumor necrosis factor (TNF) pathway." (PMID 35295950, 2022). "Unexpectedly, in all four primary thymoma epithelial cell cultures tested, cFLIP knockdown induced autophagosome formation and rendered pTECs sensitive to TNFα-induced cell death that could not be prevented by single agent pan-caspase and necroptosis inhibition." (PMID 29163772, 2017).
Whipple disease (7 papers, 2012 to 2025). A systemic infection caused by the Gram-positive bacterium Tropheryma whipplei. "Exacerbation of subacute Whipple’s disease should be added to the list of possible side effects of therapy with these agents, especially TNFα antagonists." (PMID 26282628, 2015). "We report two cases of Whipple’s disease diagnosed in the context of an inflammatory disease with anti-tumor necrosis factor alpha failure." (PMID 26215452, 2015). "Studies have shown impaired Th1 responses and low serum levels of interleukin-12p40 and tumor necrosis factor-α among patients with Whipple's disease." (PMID 22988534, 2012). "Mechanistically, IRIS reflects an abrupt shift from the Th2/Treg-dominant, anergic immune profile of untreated Whipple’s disease toward an exaggerated Th1-driven cytokine response involving TNF-α, IFN-γ, and markers of microbial translocation owing to intestinal barrier dysfunction." (PMID 41583294, 2025). "Interestingly, clinical evidence suggests that patients with a history of immunosuppression or receipt of immunosuppressive agents, especially TNFα inhibitors, were more likely to develop systemic Whipple’s disease with rapid deterioration directly or soon after medication onset." (PMID 39068468, 2024). "Whipple’s disease should be suspected in all patients diagnosed with chronic inflammatory rheumatism, partially controlled or not controlled by treatment with tumor necrosis factor alpha blockers, whose condition worsens after treatment." (PMID 26215452, 2015).
xerostomia (7 papers, 2017 to 2025). Dryness of the mouth resulting from reduced salivary secretion. "Salivary cortisol, TNF-α, and IL-6 were measured in three RCTs; oral salivary flow rate was examined in two RCTs; and the association between xerostomia and BMS was investigated in one RCT." (PMID 37814265, 2023). "Among the inflammatory cytokines assessed - IL-6, TNF-α, IFN-γ, IL-10, IL-12p70, IL-1β, IL-8, IL-13, IL-2, IL-5, IL-7 and IL-17A, xerostomia correlated with lower levels of saliva IL-2 and TNF-α, and elevated levels of serum IL-12p70 and IL-10 (p < 0.05)." (PMID 36846089, 2023). "Based on the one-way analysis of variance (ANOVA), the individuals who experienced dry mouth had significantly lower levels of saliva IL-2 and TNF-α, and higher levels of serum IL-12p70 and IL-10." (PMID 36846089, 2023). "We did not observe any associations between levels of IL-6, IL-8, IP-10, TARC, TNF, and ENA-78 in the HNC survivors who reported xerostomia, dysphagia, and CF scores above thresholds, and those who did not." (PMID 36350483, 2022). "Our data support that MSC(SG) treated with IFNγ and TNFα could serve as a therapeutic tool to treat radiation-induced xerostomia." (PMID 41323369, 2025). "However, there were no significant improvements in TNF-α levels, salivary flow, and the association between xerostomia and BMS." (PMID 37814265, 2023). "Our objective is to compare MSC(SG) to more traditional MSC sources including MSC(AD) and MSC(BM), evaluating the effects of cytokine stimulation (IFNγ and TNFα) on the trophic secretome and function of MSC(SG) in the treatment of radiation-induced xerostomia." (PMID 41323369, 2025). "We found that saliva IL-2 and TNF-α levels were lower, and serum IL-12p70 and IL-10 (p < 0.05) higher in patients with xerostomia than those without." (PMID 36846089, 2023).
adult-onset Still disease (6 papers, 2010 to 2022). A rare inflammatory multisystem disorder characterized clinically by fever of unknown origin, arthralgia or arthritis, hyperleucocytosis, and typical skin rash. "Among other cytokines, IL-18 is thought to play a pivotal role in the inflammatory cascade in patients with adult-onset Still disease by orchestrating the Th1 response and inducing other cytokines, such as IL-1β, IL-8, tumor necrosis factor-α TNF-α and IFN-γ." (PMID 20565717, 2010). "Adult-onset Still’s disease (AOSD) is a self-inflammatory disease showing macrophage and neutrophil activation by inflammatory cytokines such as TNF-α, IL-6, and IL-18." (PMID 33627085, 2021). "Adult-onset Still’s disease (AOSD) is a self-inflammatory disease exhibiting macrophage and neutrophil activation by inflammatory cytokines such as tumor necrosis factor-α (TNF-α), interleukin-6 (IL-6), and interleukin-18 (IL-18)." (PMID 33627085, 2021).
ANCA-associated vasculitis (6 papers, 2017 to 2022). "The critical role of TNFα in ANCA-associated vasculitis have been widely reported, mainly as the function of priming and activating neutrophils." (PMID 36505410, 2022). "As TNF-α is involved in several pathogenetic steps known to be involved in ANCA-associated vasculitis, several clinical trials have been conducted almost two decades ago." (PMID 33023023, 2020). "Additionally, high expression levels of serum IFN-ɤ and TNF-α were observed in patients with myeloperoxidase-antineutrophil cytoplasmic antibody-associated vasculitis who were positive for anti-moesin auto-Ab." (PMID 34577564, 2021). "The other two cases were associated with RA and ANCA-associated vasculitis, respectively, and were selected by the department of rheumatology to receive molecularly targeted agents other than TNF inhibitors, because of their advanced age and poor general condition." (PMID 35008766, 2021). "The rate of severe and limited flares was comparable between both treatment arms, so it might be concluded that TNF-α inhibition has a limited effect on the maintenance of remission and thus plays no role in the management of ANCA-associated vasculitis." (PMID 33023023, 2020).
angioedema (6 papers, 2013 to 2025). Swelling involving the deep dermis, subcutaneous, or submucosal tissues, representing localized edema. "IL-1 and TNF-α can enhance the activation of the prekallikrein–high-molecular-weight kininogen complex, which is the initiating event of an angioedema attack." (PMID 36422280, 2022). "Responders had CSU or CAU with and without angioedema, whereas patients with DPU or NU did not respond to treatment with TNF-alpha inhibitors." (PMID 24167521, 2013).
basophilic leukemia (6 papers, 2017 to 2025). "Anti-allergic activities of A40 were confirmed based on inhibitory effects on IL-4 and tumor necrosis factor alpha (TNF-α) production in compound (com) 48/80-induced rat basophilic leukemia (RBL)-2H3 cells." (PMID 38037338, 2024). "USF2690 was found to be an inhibitor of β-hexosaminidase release and tumor necrosis factor (TNF)-α, and 9nterleukin (IL)-4 secretion from rat basophilic leukemia (RBL-2H3) cells, with IC50 values of 2.8, 2.9, and 2.8 μM, respectively." (PMID 35050002, 2022). "Aucubin has been shown to inhibit TNF-alpha and IL-6 production in antigen-stimulated rat basophilic leukemia-2H3 mast cells." (PMID 28153003, 2017).
biliary atresia (6 papers, 2006 to 2021). A rare, biliary tract disease characterized by progressive obliterative cholangiopathy of the intra- and extrahepatic bile ducts, occurring in the embryonic/ perinatal period, leading to severe and persistent neonatal jaundice and acholic stool. "Previously, it has been shown that IFN-γ and TNF-α play important roles in the pathogenesis of biliary atresia." (PMID 23844248, 2013). "In addition, in experimental biliary atresia it has been shown the ability of TNFα to promote cholangiocyte programmed cell-death through the activation of TNFα/TNFR2 molecular pathway." (PMID 30275402, 2018). "It is consistent with higher IL-2, IL-4, IL-6, IL-10, TNFα, and IFN-γ in patients with biliary atresia." (PMID 34630385, 2021). "Here, we show that such an increase is not essential for the expression of the proinflammatory response in experimental biliary atresia, as demonstrated by the increases in mRNA levels for IFNγ, and TNFα at the onset of jaundice and acholic stools in mice lacking IL-12." (PMID 16623951, 2006).
Bovine mastitis (6 papers, 2017 to 2025). INFLAMMATION of the UDDER in cows. "The development of bovine mastitis is closely associated with the overexpression of pro-inflammatory cytokines, particularly IL-1β, IL-6, and TNF-α, which play pivotal roles in inflammatory cascades." (PMID 40901059, 2025). "It is well-studied that proinflammatory cytokines, such as TNF-α and IL-6, play a central role in the inflammatory response associated with bovine mastitis." (PMID 40577324, 2025). "Pathological conditions cause altered expression levels of pro-inflammatory cytokines, such as TNF-α, which is produced early in the inflammatory response, IL-1β, which is crucial for both adaptive and innate immunity, and IL-6, which is thought to be one of the main biomarkers of bovine mastitis." (PMID 40005856, 2025).
calculus (6 papers, 2014 to 2025). "TNF-α in the group of patients with urolithiasis was significantly higher than those in the control group." (PMID 36830821, 2023). "We also showed that, unlike leptin, ghrelin correlates with other outcomes such as IL-6, TNF-α, and UA only in the group of people with urolithiasis which may be helpful in further research on appetite hormones in patients with this condition." (PMID 36830821, 2023).
cellulitis (6 papers, 2016 to 2025). Inflammation of the dermis and subcutaneous tissues caused by a bacterial infection. "Our results revealed that TNF inhibitors were associated with an increased risk of cutaneous bacterial infections; 67% were cellulitis." (PMID 38660962, 2024).
central nervous system lymphoma (6 papers, 2020 to 2024). "The ligands of the tumor necrosis factor (TNF) family (APRIL and BAFF) showed high specificity and sensitivity in the diagnosis of central nervous system lymphoma." (PMID 33885377, 2021). "Notably, one of these compounds, NGR-TNF (consisting of CNGRCG peptide fused to tumor necrosis factor-alpha), has been tested in patients with relapsing/refractory primary central nervous system lymphoma (PCNSL), with evidence of antitumor efficacy and good tolerability." (PMID 38289472, 2024).
cherubism (6 papers, 2014 to 2025). Cherubism is a rare, self-limiting, fibro-osseous, genetic disease of childhood and adolescence characterized by varying degrees of progressive bilateral enlargement of the mandible and/or maxilla, with clinical repercussions in severe cases. "This systemic inflammation is rescued when SH3BP2 KI mice are crossed with mice deficient in either TNF-α or MYD88 (a mediator of toll-like receptor signaling) indicating that cherubism is an auto-inflammatory bone disease." (PMID 41019663, 2025). "While studying the molecular mechanisms underlying cherubism, a bone disease characterized by systemic inflammation, a link was identified between tankyrases 1 and 2 and tumor necrosis factor alpha (TNFα) expression." (PMID 33923319, 2021). "A mouse model has been developed to study Cherubism and has revealed that the Cherubism mutation (Pro416Arg) results in bone resorption, and increased levels of TNF-α, a cytokine known to increase osteoclast recruitment." (PMID 25409853, 2014). "We also explored the potential role of TNF-α in the pathogenesis of human cherubism, and searched for potential biomarkers of the disease." (PMID 30236129, 2018). "Studies of mouse models of cherubism suggest that TNF-α plays a key role in the disorder by enhancing osteoclast and macrophage differentiation." (PMID 30236129, 2018). "A recent report shows that an anti-TNF-α antagonist (Etanercept) can prevent or ameliorate the disease progression in Cherubism mice." (PMID 25409853, 2014). "The role of TNF-α in the etiology of cherubism is under debate and could be different between murine and human cherubism." (PMID 41019663, 2025). "All these theories may explain a supposed more accessory role of TNF-α in human cherubism." (PMID 30236129, 2018). "Although TNF‐α plays a key role in disease pathogenesis in mice, anti‐TNF‐α therapy resulted in no significant improvement in Cherubism patients, suggesting that the mechanism underlying human cherubism may be different from that of mice." (PMID 35757898, 2022). "Moreover, we demonstrated that the mechanism underlying human cherubism is different from that of mice; since, contrary to mice, it does not seem that TNF-α underlies the physiological mechanism of human cherubism, and that RANK-RANKL-OPG triad is not playing their usual role." (PMID 30236129, 2018). "As cherubism was recently described as being an auto-inflammatory bone disease, we focused on the expression of genes involved in osteoclastogenesis (RANK, RANKL, M-CSF, OPG, NFATc1), bone formation (ALP, Osteocalcin), and inflammation (IL6, IL6R, TNFα, TNFR1, TNFR2, IL17)." (PMID 30236129, 2018). "Although Steroids, TNF-α inhibitors, calcitonin, anti-neoplastic agents, immunosuppressants, and monoclonal antibodies have been reported as an option for the pharmacological treatment of cherubism, none have yet been confirmed by clinical trials as a possibility for effective treatment." (PMID 38902663, 2024).
chronic apical periodontitis (6 papers, 2014 to 2024). Chronic form of periapical periodontitis. "Increased TNF-α levels have also been identified in primarily infected root canals and the infected periapical tissue of patients with pulpitis and chronic periapical periodontitis." (PMID 24970360, 2014).
coronary artery stenosis (6 papers, 2015 to 2024). "We identified relevant inflammatory biomarkers (MCP-4, AA, hs-CRP, and TNF-α) of severe carotid artery stenosis and coronary artery stenosis and toxicological effects of inflammatory response on carotid artery stenosis and multivessel coronary artery stenosis in elderly patients." (PMID 34976297, 2021). "In this group, inflammatory cytokines TNFα and IL6 were the main factors directly related to the severity of coronary stenosis." (PMID 37762433, 2023). "SAH, IL-1β, Hcy, TNF-α and BDNF in serum of patients with CHD can be used as effective biological indicators to monitor the degree of CHD and severity of coronary stenosis." (PMID 35282820, 2022). "The correlation analysis of SAH, IL-1β, Hcy, TNF-α, BDNF and the number of coronary artery stenosis was conducted by Kendall’s tau-b correlation, respectively." (PMID 35282820, 2022). "The present study demonstrated that the levels of TNF-α, TLR4, ACR, MDA, and hs-CRP as proinflammatory and prooxidant mediators were increased greatly in elderly patients with severe coronary stenosis and multiple coronary chronic total occlusions." (PMID 31780868, 2019). "Levels of TNF-α, TLR4, ACR, MDA, and hs-CRP were remarkably increased (P < 0.001), and levels of SDF-1α, SOD3, and eNOS were remarkably lowered (P < 0.001) in elderly patients with severe coronary stenosis and multiple coronary chronic total occlusions." (PMID 31780868, 2019).